DMPK (DM1 protein kinase)
Diseases named in the same sentence as DMPK in open-access papers (continued):
Sharing a sentence is not in itself a finding about the gene and the disease.
myotonic dystrophy (continued). "In another example, myotonic dystrophy (MD) which commonly presents in patients as muscular degeneration, is also characterized by aberrant RNA splicing; CUG triplet repeat (CUGBP) has been specifically linked to MD through its interaction with myotonic dystrophy protein kinase (DMPK) mRNA." (PMID 33923168, 2021). "Interestingly, model mice acutely overexpressing a normal-length DMPK 3′ UTR mRNA reproduced cardinal features of myotonic dystrophy, including myotonia, cardiac conduction abnormalities, histopathology and RNA splicing defects in the absence of detectable nuclear inclusions." (PMID 26515653, 2015). "For example, DM1 myotonic dystrophy, a trinucleotide repeat in the 3' UTR of the DMPK gene results in sequestration of the splicing regulator MBNL1, and this in turn causes defects in muscle gene expression, particularly alteration of splicing patterns." (PMID 33561245, 2021). "This concept originated from the pathogenesis of myotonic dystrophy, where a CUG triplet expansion in the promoter of the DMPK gene leads to the formation of intranuclear inclusions." (PMID 32777047, 2020). "Repeat expansions of the CTG trinucleotide in the non-coding 3′-UTR of the myotonic dystrophy protein kinase gene (DMPK) and of CCTG repeats in intron 1 of the Zinc Finger Protein 9 gene (ZNF9) lead to myotonic dystrophy (DM1) and myotonic dystrophy type 2 (DM2) respectively." (PMID 35646086, 2022). "Normal length of the DMPK gene CTG and ZNF9 gene CCTG repeats excluded myotonic dystrophy." (PMID 32407401, 2020). "Since SRF regulates DMPK in SMC, we hypothesized that alteration of L-type calcium channel expression by DMPK, resembling the regulatory pathway of the myotonic dystrophy model, is responsible for the functional changes of Srf KO SMC." (PMID 28152551, 2017). "This makes the adult-onset DM1 and EDM1 mouse models, which have robust multi-systemic phenotypes and utilize the doxycycline inducible EGFP DMPK 3′UTR, a useful model to test many of the ever increasing number of therapeutic options aimed at treating myotonic dystrophy." (PMID 24039817, 2013).
muscular dystrophy (25 papers, 2011 to 2025). Muscular dystrophy (MD) refers to a group of more than 30 genetic diseases characterized by progressive weakness and degeneration of the skeletal muscles that control movement. "DM1 is an inherited muscular dystrophy which is caused by an abnormal amount of CTG trinucleotide repeats in the 3′ untranslated region of the dystrophia myotonica protein kinase (DMPK) gene." (PMID 33806433, 2021). "Five expansions in DMPK were detected, including in a child and a mother with a clinical diagnosis of muscular dystrophy, in two siblings with suspected distal myopathy, and in an adolescent with congenital myopathy (patients 54–58)." (PMID 35182509, 2022). "DM1 is the most common form of muscular dystrophy in the adult and is caused by an expansion of CTG repeats in the 3′-untranslated region of the myotonic dystrophy protein kinase (DMPK) gene." (PMID 34205993, 2021). "Myotonic dystrophy type I (DM1) is the most common form of adult muscular dystrophy, caused by expansion of a CTG triplet repeat in the 3′ untranslated region (3′UTR) of the myotonic dystrophy protein kinase (DMPK) gene." (PMID 32971903, 2020). "DM1 is the most common form of muscular dystrophies in adults, and is caused by abnormal expansion of CTG repeats in the 3′ untranslated region of the myotonic dystrophy protein kinase (DMPK) gene on chromosome 19 9,10." (PMID 32054946, 2020). "Myotonic dystrophy type 1 (DM1; MIM#160900) is a debilitating form of muscular dystrophy due to an abnormal increase of CTG repeats in the 3′ UTR region of the dystrophia myotonica protein kinase gene (DMPK)." (PMID 30341284, 2018). "DM1 is the most common form of muscular dystrophy in adults, caused by an expanded CTG repeat in the 3′UTR of the dystrophia myotonica protein kinase (DMPK) gene." (PMID 28377694, 2017). "DMPK functions to protect against muscular dystrophies by balancing the antagonistic activities of two RNA-binding proteins, CUGBP1 (CELF1) and MBNL1, whose dysregulation can lead to abnormal splicing of ion channels, including the voltage-gated calcium channel." (PMID 28152551, 2017). "It seems possible therefore that the mis-regulation of CELF1 in DM1 may contribute to pathogenesis by disrupting secretion of ECM and/or other extracellular proteins resulting in a muscular dystrophy despite the fact that the gene affected in DM1, DMPK, does not encode an ECM component." (PMID 28129347, 2017).
Myotonia (18 papers, 2015 to 2026). An involuntary and painless delay in the relaxation of skeletal muscle following contraction or electrical stimulation. "Myotonic Dystrophy type I (DM1) is a multisystemic disorder caused by expanded CTG triplet repeats in the 3’UTR of the DMPK (Dystrophia Myotonica Protein Kinase) gene that leads to muscle wasting, weakness and inability to relax (myotonia)." (PMID 38769542, 2024). "DM1 is caused by an unstable (CTG)n repeat in the DMPK gene and characterized by skeletal muscle weakness, muscle wasting, and myotonia." (PMID 31649961, 2019). "This differential progression pattern may reflect distinct underlying pathophysiological mechanisms, with myotonia primarily resulting from altered chloride channel function due to DMPK gene effects, while weakness stems from progressive muscle fiber degeneration and replacement." (PMID 40863987, 2025). "DM1 is caused by a pathogenic CTG expansion in DMPK (>50 repeats) which results in altered splicing of CLCN1, as well as other genes, leading to reduced chloride conductance and myotonia." (PMID 32670189, 2020). "It is a hereditary neuromuscular disorder with progressive muscle weakness and myotonia, caused by an unstable cytosine-thymine-guanine (CTG) repeat expansion in the 3′-untranslated region of the dystrophia myotonica protein kinase (DMPK) gene." (PMID 27015655, 2016). "In the case of DM1 disease, DMPK may be related to myotonia and also could be involved indirectly or directly with the cytoskeleton myosin phosphatase target subunit (MYPT1), serum response transcription factor (SRF), and the nuclear envelope protein lamin A/C." (PMID 33673200, 2021). "The presence of expanded CTG repeats in DMPK mRNAs leads to the sequestration of RNA‐binding factors such as the Muscleblind‐like (MBNL) proteins, resulting in widespread splicing defects that contribute to progressive muscle weakness and myotonia." (PMID 41250834, 2025). "Weakness was more often reported in individuals with dystrophic myotonia than non-dystrophic myotonia, with 90.8% (n = 79) of individuals with DMPK expansions and 90% (n = 9) with CNBP expansions reporting this as a symptom." (PMID 32670189, 2020). "Due to the decrease in DMPK levels, phospholamban and sarcolipine are not phosphorylated, in turn SERCA is constantly inhibited, leading to an increase concentration of calcium in the cytoplasm, causing sustained muscle contraction (myotonia)." (PMID 33673200, 2021). "Furthermore, the systemic treatment with ASO (ISIS 486178) targeted to the non-CUG sequence within the 3′-UTR of DMPK also specifically rescued DM1 phenotypes of myotonia and cardiac conduction defects in DM200 mice [a DM1 model carrying a GFP-DMPK 3′-UTR (CTG) 200 transgene]." (PMID 34867280, 2021).
cardiomyopathy (6 papers, 2008 to 2025). A disease of the heart muscle or myocardium proper. "Since TfR1 is commonly expressed in the most cell types including heart, and the mutant DMPK is the central player in DM1 cardiomyopathy, the FORCE platform can deliver ASOs specifically to cardiac and skeletal muscle." (PMID 41303475, 2025). "In addition to these, one highly differentiated (FST value 0.15–0.25) SNV rs539962979 with FST value 0.16597 was also observed in DMPK which has been reported to be involved in cardiomyopathy." (PMID 29420653, 2018). "A study by Wang and colleagues demonstrates that inducible expression of 960 interrupted CUG repeats located in the DMPK 3′UTR sequence results in the development of nuclear foci concurrent with arrhythmias, cardiomyopathy, cystolic and diastolic dysfunction and aberrant splicing." (PMID 19092997, 2008).
Insulin resistance (5 papers, 2007 to 2025). Increased resistance towards insulin, that is, diminished effectiveness of insulin in reducing blood glucose levels. "On one hand, DMPK gene mutations lead to RNA toxicity, causing abnormalities in insulin signaling pathways in skeletal muscle and adipose tissue, thus triggering insulin resistance." (PMID 41018201, 2025). "Taken together, these findings indicate that reduced DMPK expression may directly influence the onset of insulin-resistance in DM1 patients and point to dmpk as a new candidate gene for susceptibility to type 2-diabetes." (PMID 17987120, 2007). "Taken together, these findings indicate that reduced DMPK expression may directly influence the onset of insulin-resistance in myotonic dystrophy 1 patients and suggest that DMPK could represent a susceptibility gene to type 2-diabetes." (PMID 17987120, 2007). "Although RNA toxicity is widely recognized as a primary mechanism, the contribution of DMPK protein dysfunction to insulin resistance should not be overlooked." (PMID 41018201, 2025). "Myotonic dystrophy type I (DM1) leads to progressive weakness, cardiac conduction defects and insulin resistance, being characterised by a repeated CTG sequence in the 3′ UTR of the dystrophia myotonica protein kinase (DMPK) gene concomitant with massive alterations in AS patterns." (PMID 28374191, 2017).
cataract (4 papers, 2011 to 2022). Partial or complete opacity of the crystalline lens of one or both eyes that decreases visual acuity and eventually results in blindness. "In DM1, downregulation of these genes by epigenetic changes, such as hypermethylation may participate in some clinical features including cataracts, muscle defects or cardiac conduction abnormalities as observed in DMPK, SIX5 or DMWD knockdown mouse models." (PMID 35408837, 2022). "Although decreased gene expression at the DM1 locus is not sufficient to explain the complex DM1 phenotype, downregulation of DMPK, SIX5 and DMWD genes by epigenic changes in DM1 could participate in some clinical features such as DM1 cataracts, muscle defects or cardiac conduction defects." (PMID 35408837, 2022).
Arrhythmia (3 papers, 2008 to 2022). Any cardiac rhythm other than the normal sinus rhythm. "In contrast, tissue-specific and Cre-inducible EpA960 transgenic mice, which express the DMPK 3′ UTR with an interrupted CTG960 repeat at relatively high levels, display severe cardiac arrhythmias, muscle wasting and splicing defects." (PMID 24293317, 2013).
autism (3 papers, 2023 to 2025). Persistent deficits in social interaction and communication and interaction as well as a markedly restricted repertoire of activity and interest as well as repetitive patterns of behavior. "Our findings indicate that DMPK CTG expansion-associated autism arises from developmental mis-splicing." (PMID 37645891, 2023). "Here, we report that sequestration of MBNL splicing factors by mutant DMPK RNAs with expanded CUG repeats alters the RNA splicing patterns of autism-risk genes during brain development, particularly a class of autism-relevant microexons." (PMID 40259070, 2025). "We demonstrate that both DMPK-CTG expansion and Mbnl null mouse models recapitulate autism-relevant mis-splicing profiles, along with social behavioral deficits and altered responses to novelty." (PMID 40259070, 2025).
diabetes (2 papers, 2018 to 2025). "The clinical presentation of patient P5 which includes diabetes, hepatic fibrosis and marked asthenia is consistent with that reported in other women aged around 35 years of age, who have mutations in the DMPK gene." (PMID 41614819, 2025). "The DMPK gene encodes a serine-threonine kinase that is closely related to other kinases involved in the insulin secretion pathway, which helps explain the diabetes observed in P5." (PMID 41614819, 2025). "The discovery of inhibitors with desirable selectivity and DMPK properties is a key step for the development of successful 11β-HSD1 inhibitors for the treatment of GC-related disorders such as diabetes and AD." (PMID 29495550, 2018).
Glucose intolerance (2 papers, 2016 to 2025). Glucose intolerance (GI) can be defined as dysglycemia that comprises both prediabetes and diabetes. "A study using a DMPK gene knockout (dmpk−/−) mouse model revealed that dmpk−/− mice exhibited impaired insulin signaling, glucose intolerance, and reduced insulin-dependent GLUT4 transport in muscle tissue, a phenomenon not observed in fat and liver tissues, which do not express DMPK." (PMID 41018201, 2025).
Kennedy disease (2 papers, 2011 to 2025). Kennedy's disease, also known as bulbospinal muscular atrophy (BSMA), is a rare X-linked recessive motor neuron disease characterized by proximal and bulbar muscle wasting. "Trinucleotide repeat expansion disorders such as Kennedy’s disease (spinal bulbar muscular atrophy; AR gene CAG expansion) and myotonic dystrophy type 1 (Dystrophia Myotonica Protein Kinase—DMPK gene CTG expansion) are increasingly being recognized as etiologies of subfertility." (PMID 41465244, 2025).
neuronal intranuclear inclusion disease (2 papers, 2023 to 2025). Neuronal intranuclear inclusion disease (NIID) is a very rare multisystem neurodegenerative disorder characterized by the presence of eosinophilic intranuclear inclusions in neuronal and glial cells, and neuronal loss. "This technique would also allow us to define the global methylation pattern of the DMPK locus, as previously reported for other repeat expansion diseases such as neuronal intranuclear inclusion disease." (PMID 37373276, 2023).
schizophrenia (2 papers, 2021 to 2022). A major psychotic disorder characterized by abnormalities in the perception or expression of reality. "Genome analyses also identified variants with potential clinical implications, including TREs (one in DMPK; two in ATXN8OS) and ultra-rare loss-of-function SNVs in ZMYM2 (a novel candidate gene for schizophrenia)." (PMID 33526774, 2021).
Skeletal myopathy (2 papers, 2008 to 2021). "DMPK-/- mice develop a mild late-onset, progressive skeletal myopathy which suggested that DMPK might be necessary for the maintenance of skeletal muscle structure." (PMID 19516957, 2008).
asthma (1 paper, 2021). "For the two novel asthma risk loci, FCER1G was replicated on 1q23.3 (z = 5.08, PTWAS = 3.71E−7), but not DMPK on 19q13.32 (z = 1.78, PTWAS = 0.075)." (PMID 34103634, 2021).
autism spectrum disorder (1 paper, 2023). A spectrum of developmental disorders that includes autism, and Asperger syndrome. "Tandem repeat expansions are enriched in autism spectrum disorder, including CTG expansion in the DMPK gene that underlines myotonic muscular dystrophy type 1." (PMID 37645891, 2023).
AV block (1 paper, 2025). "Even heterozygous DMPK+/− mice develop first-degree AV block similar to DM1 patients, indicating that cardiac conduction is very sensitive to DMPK gene products." (PMID 41303475, 2025).
breast carcinoma (1 paper, 2018). "Sixteen understudied kinases showed strong variance between TNBC and HER2/luminal breast cancer, with higher-ranked understudied kinases being DAPK3, ADCK1, MRCKA (CDC42BPA), STK17A, DMPK and VRK2." (PMID 29643987, 2018).
cryptosporidiosis (1 paper, 2025). Intestinal infection with organisms of the genus Cryptosporidium. "If this DMPK profile of high M2 exposure is recapitulated in humans as predicted by in vitro hepatocyte metabolism studies, the auxiliary exposures of M2 may be important for treating biliary and pulmonary infections in exceptional cases of cryptosporidiosis." (PMID 40737275, 2025).
delirium (1 paper, 2025). A disorder characterized by confusion; inattentiveness; disorientation; illusions; hallucinations; agitation; and in some instances autonomic nervous system overactivity. "There were eight protective genes (DHODH,DHRS7B,TOP1MT,CASP8,GFM1,CPT1B,TK2,GPD2), and four genes (SCP2,DMPK,GSTK1,SIRT3) that increased delirium risk, as shown inFigure 2, withp = 0.05 (dotted line); and false discovery rate (FDR) < 0.05 (red asterisks)." (PMID 41330563, 2025). "Meanwhile, higher expression ofSCP2,DMPK,GSTK1, andSIRT3might increase the risk of delirium." (PMID 41330563, 2025).
myotonic syndrome (1 paper, 2022). "There was only one case in which rapid ES did not identify a pathogenic variant that was identified on a different genetic test—an infant with congenital myotonic dystrophy for whom a myotonic syndrome gene panel identified the pathogenic expansion in DMPK (OMIM 160900)." (PMID 36064943, 2022).
pancreatic adenocarcinoma (1 paper, 2018). "ADCK1, DAPK3, DMPK STK17A and VRK2 were found to be similarly amplified in other cancers including prostate adenocarcinoma, uterine carcinosarcoma and pancreatic adenocarcinoma." (PMID 29643987, 2018).
rhabdomyosarcoma (1 paper, 2021). A rare aggressive malignant mesenchymal neoplasm arising from skeletal muscle. "Under oxidative stress conditions, HK2 association to mitochondria in rhabdomyosarcoma cells is regulated by Myotonic Dystrophy Protein Kinase (DMPK) and Src kinase in a multi-molecular complex characterized by antioxidant and pro-survival properties involved in muscle fiber differentiation." (PMID 33946854, 2021).
neuromuscular disease (17 papers, 2013 to 2023). "DM1 is a neuromuscular disease caused by an expanded trinucleotide tract of CTG repeats within the 3′ untranslated region of the DMPK gene." (PMID 37882878, 2023). "Among the trinucleotide repeat disorders, myotonic dystrophy type 1 (DM1) is one of the most complex neuromuscular diseases caused by an unstable CTG repeat expansion in the DMPK gene." (PMID 35408837, 2022). "Myotonic dystrophy type 1 (DM1) is a rare neuromuscular disease originating from an abnormal expansion of a CTG microsatellite in the 3′ untranslated region of the DM1 protein kinase (DMPK) gene." (PMID 37744174, 2023). "It is an autosomal dominant inherited neuromuscular disease having abnormally expanded CTG repeats in DMPK on chromosome 19q 13.3." (PMID 34114984, 2021).
autosomal dominant disease (10 papers, 2013 to 2025). Autosomal dominant form of disease. "DM1 is an autosomal dominant disease caused by unstable expanded cytosine–thymine–guanine (CTG) repeats within the 3′ untranslated region (3′ UTR) of the DMPK (Dystrophia Myotonica Protein Kinase; OMIM* 605377) gene at chromosome 19q13.3." (PMID 40508159, 2025). "DM1 is an autosomal dominant disease associated with an abnormal repetition of the cytosine-thymine-guanine (CTG) triplet in the 3′ untranslated region of the protein kinase DM1 (DMPK) gene on chromosome 19q13.3." (PMID 37047859, 2023). "DM1 is an autosomal dominant disease caused by an expansion of unstable CTG repeats located within the 3′-UTR of the dystrophia myotonica protein kinase (DMPK) gene." (PMID 30298045, 2018). "It is an autosomal dominant disease caused by a nucleotide repeat expansion of cytosine–thymine–guanine (CTG) in the 3′ untranslated region (UTR) of the dystrophia myotonica protein kinase (DMPK) gene." (PMID 36230978, 2022). "DM1 is an inherited autosomal dominant disease caused by the dynamic and unstable expansion of a trinucleotide CTG repeat motif in the 3′ UTR of the DMPK gene located at q13.3 on chromosome 19." (PMID 24409116, 2014).